NLRP3 (NLR family pyrin domain containing 3)
Diseases named in the same sentence as NLRP3 in open-access papers (continued):
Sharing a sentence is not in itself a finding about the gene and the disease.
anxiety disorder (5 papers, 2019 to 2024). A category of psychiatric disorders which are characterized by anxious feelings or fear often accompanied by physical symptoms associated with anxiety. "Taken together, our data revealed the pivotal role of NLRP3 inflammasome activation in the regulation of fear memory and the development of PTSD and anxiety disorder, providing a novel target for the clinical treatment of such disorders." (PMID 32635937, 2020).
autism (5 papers, 2023 to 2025). Persistent deficits in social interaction and communication and interaction as well as a markedly restricted repertoire of activity and interest as well as repetitive patterns of behavior. "Accumulating data had proven that the crosstalk between TLR4, NF-κB, and NLRP3 inflammasome is the keystone of the pathogenic events that occur in autism." (PMID 39596986, 2024). "Research has demonstrated the activation of multiple inflammatory complexes in autism, and one of them is NLRP3." (PMID 39401991, 2025). "tVNS application increased brain NLRP3 levels and reduced serum IL‐1β and IL‐22 levels in the autism model." (PMID 39401991, 2025). "Agents that interfere with TLR4/NF-κB/NLRP3 inflammasome signaling in the hippocampal tissues were proven to significantly mitigate the neuroimmune dysregulation frequently encountered in autism." (PMID 39596986, 2024). "Brain NLRP3 levels were significantly higher in both sexes in the VPA autism model (P < 0.05)." (PMID 39401991, 2025). "NLRP3 inflammasome activation is predicted to have an essential place in the development of autism." (PMID 39401991, 2025). "ST36 acupuncture inhibited NLRP3 inflammasome activation and alleviated prefrontal cortex‐related behavioral impairment in a study utilizing VPA‐induced rat models of autism." (PMID 39401991, 2025).
behavioral disorders (5 papers, 2020 to 2024). "These behavioral disorders caused oxidative stress damage in the hippocampus and changes in NLRP3, IL‐1β and BDNF levels." (PMID 39443283, 2024). "In our in vivo studies, compared to MPTP group, mice in MPTP + BBR group showed significant amelioration of behavioral disorders, mitigation of neurotoxicity and NLRP3-associated neuroinflammation, enhancement of the autophagic process in substantia nigra (SN)." (PMID 33584302, 2020). "Knockdown of NLRP3 in the SNc region ameliorates behavioral disorders and exerts protective effects on DA neurons in PD model mice." (PMID 36199191, 2022).
benign prostatic hyperplasia (5 papers, 2016 to 2025). A non-cancerous nodular enlargement of the prostate gland. "We also investigated hypoxia-induced induction of NLRP3 receptor and activation of the NLRP3 inflammasome in human benign prostate hyperplasia (BPH) cell line BPH-1, which exhibit a constitutively active NF-κB." (PMID 27058421, 2016). "Prdx3 has been reported to promote pyroptosis in benign prostatic hyperplasia (BPH) and also act as a suppressor of pyroptosis by inhibiting NLRP3 inflammasome activation." (PMID 38007535, 2023).
Calcium oxalate nephrolithiasis (5 papers, 2021 to 2025). The presence of calcium- and oxalate-containing calculi (stones) in the kidneys. "In an animal study, activation of the NLRP3 inflammasome led to calcium oxalate nephrolithiasis." (PMID 35629321, 2022). "Since inflammation plays a pivotal role in disease progression in oxalate nephrolithiasis, we then tested whether changes in inflammasome NLRP3 expression could be found in oxalate-treated cells." (PMID 34201387, 2021).
chorioamnionitis (5 papers, 2019 to 2023). A morphologic finding indicating inflammation of the fetal sac membranes. "Concurrent infections including lower genital infections and chorioamnionitis would be expected to be contributory by enhancing activation of the NLRP3 inflammasome, especially with intra-amniotic infection." (PMID 31771607, 2019). "Interestingly, the immune response induced by inoculation with U. parvum involves the activation of the NLRP3 inflammasome, an important pathway for preterm parturition in the context of intra-amniotic infection (51, –, 53)." (PMID 32576673, 2020). "A previous study reported an increased NLRP3 expression in the chorioamnion membranes in PTB, which was accompanied by an increased inflammasome activation and an increased expression of the mature form of IL-1β in spontaneous preterm labor with chorioamnionitis." (PMID 36362749, 2022).
chronic lymphocytic leukemia (5 papers, 2021 to 2024). "Intriguingly, in chronic lymphocytic leukemia samples and Burkitt lymphoma cell lines, downregulation of NLRP3 was associated with cancer progression." (PMID 35897704, 2022). "In lymphocytes derived from chronic lymphocytic leukemia patients, NLRP3 was down-modulated than it from healthy donor." (PMID 34101758, 2021). "In chronic lymphocytic leukemia (CLL), NLRP3 inflammasome downregulation was shown to contribute to tumorigenesis." (PMID 35897704, 2022). "Recent studies suggested that ibrutinib, a Bruton tyrosine kinase (BTK) inhibitor, developed for the treatment of chronic lymphocytic leukemia, may prevent NLRP3 inflammasome activation in macrophages, IL-1β secretion and subsequent development of inflammation and organ fibrosis." (PMID 34099830, 2021).
coagulation disorders (5 papers, 2020 to 2025). "Considering the correlation of PE with NLRP3 and all described pathomechanisms, this inflammasome appears to play a significant role in development of PE associated coagulopathy." (PMID 32650532, 2020). "In summary, the present study confirmed that intestinal I/R could cause coagulation disorders and the activation of NF-κB and NLRP3 inflammasome in rats." (PMID 32587471, 2020). "For example, in both pathologies, NLRP3 inflammasome (hyper)activation may be crucial in the consolidation of coagulation disorders within the female reproductive organs." (PMID 35785029, 2022). "If it could inhibit the activation of the NF-κB/NLRP3 pathway, it could not only attenuate the inflammatory response and protect the intestine but also inhibit the TF level and weaken coagulation disorders." (PMID 32587471, 2020). "Interestingly, HRS could strikingly improve intestinal I/R-induced intestinal injury and poor survival, which might be partially related to ameliorating coagulation disorders and inflammation via inactivation of NF-κB/NLRP3 Pathway." (PMID 32587471, 2020). "Interestingly, an important finding was that HRS might significantly improve intestinal I/R-mediated coagulation disorders and inflammation, at least in part, by inhibition of activated NF-κB/NLRP3 pathway." (PMID 32587471, 2020). "This study thus emphasized upon the amelioration of coagulation disorders and inflammation by HRS as a mechanism to improve intestinal I/R-induced intestinal injury and poor survival, which might be partially related to inhibition of NF-κB/NLRP3 pathway." (PMID 32587471, 2020).
colon adenocarcinoma (5 papers, 2021 to 2025). "We found that high expression of NLRP3 is associated with poor survival and prognosis in colon adenocarcinoma." (PMID 33821998, 2021). "In summary, high expression of NLRP3 is associated with poor survival in colon adenocarcinoma." (PMID 33821998, 2021). "NLRP3 is an independent risk factor for the prognosis of colon adenocarcinoma." (PMID 33821998, 2021). "In summary, NLRP3 is an independent risk factor for the prognosis of colon adenocarcinoma." (PMID 33821998, 2021). "In the present study, we novelty applied the human TMA cases of CRC patients to determine the NLRP3 expression in colon adenocarcinoma tissues of a human." (PMID 33821998, 2021). "In the present study, high expression of NLRP3 correlated with poor 5- and 10-year survival in colon adenocarcinoma." (PMID 33821998, 2021). "In conclusion, high NLRP3 expression predicts poor progression and survival in colon adenocarcinoma." (PMID 33821998, 2021). "Sixty pairs of human TMA cases were analyzed to assess the expression level of NLRP3 in human colon adenocarcinoma tissues and paracancerous tissues." (PMID 33821998, 2021). "Compared with that in corresponding paracancerous tissues, the expression of NLRP3 in colon adenocarcinoma tissues was higher in 49 cases and lower in 11 cases." (PMID 33821998, 2021). "It was found that NLRP3 expression was significantly up-regulated in colon adenocarcinoma tissues compared with corresponding paracancerous tissues, which is consistent with that in xenograft mice." (PMID 33821998, 2021). "Our results shed light on the role of NLRP3 as a putative prognostic biomarker of colon adenocarcinoma and a potential therapeutic target in CRC treatments." (PMID 33821998, 2021). "IOD results further confirmed that NLRP3 was significantly higher in colon adenocarcinoma tissues compared to the normal colons in both HCT116 xenografts (1.95 ± 0.43 vs. 1.00 ± 0.28, P=0.035) and RKO xenografts (2.52 ± 0.43 vs. 1.00 ± 0.25, P=0.003)." (PMID 33821998, 2021). "In the present study, we found that NLRP3 is up-regulated in colon adenocarcinoma tissues of human TMA, HCT116, and RKO xenografts." (PMID 33821998, 2021). "Importantly, based on the staining index, a significant up-regulation of NLRP3 expression was found in colon adenocarcinoma tissues compared with corresponding paracancerous tissues (5.6 ± 2.7 vs. 3.7 ± 1.8, P<0.01)." (PMID 33821998, 2021). "It indicated that high NLRP3 expression (P=0.020), elder than 65 in age (P=0.037), metastasis (P=0.004), and positive lymph nodes (P=0.002) were able to predict the poor prognosis of colon adenocarcinoma independently." (PMID 33821998, 2021). "Similarly, the protein level of NLRP3 quantified by Western blot was remarkably increased in colon adenocarcinoma tissues compared with corresponding paracancerous tissues (1.82 ± 0.34 vs. 1.00 ± 0.24, P=0.023)." (PMID 33821998, 2021). "However, in colon adenocarcinoma tissues, intense positive staining of NLRP3 was found in the cytoplasm of CRC cells." (PMID 33821998, 2021). "In summary, high expression of NLRP3 predicts advanced TNM stage, the occurrence of distant metastasis, and vascular invasion, and positive lymph nodes in human colon adenocarcinoma." (PMID 33821998, 2021).
corneal disease (5 papers, 2020 to 2025). "Collectively, these findings demonstrate a physiological role for NLRP3 and caspase-1 in regulating infection in a clinically relevant murine model of blinding corneal disease." (PMID 37730693, 2023). "We also found that corneal disease severity, neutrophil recruitment, and IL-1β secretion in infected corneas are dependent on Hla production, and that IL-1β secretion by neutrophils in vitro is dependent on Hla activation of the NLRP3 inflammasome." (PMID 41415470, 2025). "In other corneal diseases, including DED and alkali burn injury, NLRP3 activation has been shown to drive inflammation through IL-1β and IL-18 production." (PMID 40943162, 2025). "In the current study, we demonstrate that Hla is important in neutrophil secretion of IL-1β following assembly of the NLRP3 inflammasome, and that neutrophil derived IL-1β plays an important role in a murine model of MRSA keratitis where it regulates corneal disease severity and bacterial killing." (PMID 41415470, 2025). "Overall, these findings support a role for NLRP3 and caspase-1 in regulating bacterial killing and corneal disease severity with no apparent role for NLRC4 and no requirement for GSDMD, GSDME, or neutrophil elastase." (PMID 37730693, 2023). "Also, in P. aeruginosa infection, NLRP3 and caspase-1, but not NLRC4 were required for IL -1β production, bacterial killing and corneal disease severity." (PMID 37730693, 2023).
cyst (5 papers, 2022 to 2024). A sac-like closed membranous structure that may be empty or contain fluid or amorphous material. "We tested whether ADPKD cyst cells could activate the NLRP3 inflammasome using established methods to maximally prime and trigger this activation." (PMID 36523654, 2022). "Similar HCQ inhibition of this channel in vivo could restrain fluid secretion and cyst growth in PKD mice, in addition to its inhibitory effects on the NLRP3 inflammasome." (PMID 36523654, 2022).
diabetic foot ulcer (5 papers, 2020 to 2025). "Sustained activation of NLRP3 inflammasome and release of neutrophil extracellular traps (NETs) impair wound healing of diabetic foot ulcers (DFUs)." (PMID 32963812, 2020). "Through investigation of the regulatory mechanisms driving excessive NLRP3-dependent inflammation in diabetic foot ulcers, the authors discovered that the thioesterase palmitoyl-protein thioesterase 1 (PPT1) regulates NLRP3 stability through de-acylation of NLRP3 at Cys-8." (PMID 39838868, 2025). "However, under diabetic conditions, the hyperactivation of the NLRP3 inflammasome led to delayed corneal wound closure and impaired nerve regeneration, which is in line with the findings from diabetic skin wound healing and diabetic foot ulcer 36-38." (PMID 35002527, 2022).
Duchenne muscular dystrophy (5 papers, 2021 to 2023). Duchenne muscular dystrophy (DMD) is a neuromuscular disease characterized by rapidly progressive muscle weakness and wasting due to degeneration of skeletal, smooth and cardiac muscle. "Previous studies revealed an upregulation of the NLRP3 inflammasome in age-related neurodegenerative disorders such as Parkinson’s disease and Alzheimer’s disease, but also in Duchenne muscular dystrophy." (PMID 37445853, 2023). "In skeletal muscle, an upregulation of NLRP3 was shown in Duchenne muscular dystrophy and in Valosin-Containing Protein (VCP) Myopathy." (PMID 37445853, 2023). "A study by Boursereau and colleagues showed that adiponectin decreased the expression of NLRP3 inflammasome through miR-711 and attenuated muscle inflammation in Duchenne muscular dystrophy." (PMID 36114541, 2022).
enterovirus infection (5 papers, 2019 to 2025). "However, prior work has also implicated a role for the NLRP3 inflammasome in enterovirus infection, including activation of the NLRP3 inflammasome during CVB3 infection in mice and human cell lines." (PMID 33410748, 2021). "Recent studies have shown that enterovirus infection can activate the NLRP3 inflammasome, and that enterovirus 2B and 3D proteins can trigger NLRP3 inflammasome activation during EV71 and CVB3 infection." (PMID 37243164, 2023). "NLRP1 and NLRP3 have distinct expression patterns including in epithelial cells, which are important targets of enterovirus infection." (PMID 33410748, 2021). "Therefore, NLRP3 inflammasome activation is critical in defending the host from enterovirus infection." (PMID 30858838, 2019). "In this review, we discuss the NLRP3 activation pathway that is induced by enterovirus infection, the role of NLRP3 activation in the pathogenesis of EVs infection, and the role of EVs non-structure proteins in the activation and/or inhibition of the NLRP3 inflammasome." (PMID 30858838, 2019).
Erythema (5 papers, 2019 to 2025). Redness of the skin, caused by hyperemia of the capillaries in the lower layers of the skin. "For example, an NLRP1 inflammasome inhibitor may be effective in patients with LN complicated by arthritis or erythema; an NLRP3 inflammasome inhibitor may be more effective in LN patients with NP-SLE." (PMID 35664004, 2022). "Although the NLRP3 inflammasome clearly exacerbates AD symptoms such as erythema and pruritus, drugs for AD patients targeting the NLRP3 inflammasome are still lacking." (PMID 37175425, 2023). "Livedo reticularis was only seen among NLRP12 (N=2) or digenic NLRP3/NLRP12 (N=2) patients, but not in the largest NLRP3 group, though patchy erythema was seen in all groups." (PMID 38343435, 2023).
focal segmental glomerulosclerosis (5 papers, 2020 to 2025). A renal disorder characterized by sclerotic lesions in the glomeruli. "In a doxorubicin-induced mouse model of focal segmental glomerulosclerosis, astaxanthin elicits significant improvements in glomerular and interstitial fibrosis by promoting Nrf2 expression and inhibiting the NLRP3 inflammasome." (PMID 33390969, 2020). "In patients with focal segmental glomerulosclerosis (FSGS), necroptosis, a pro-inflammatory lytic form of programmed cell death activated in podocytes, activates the NLRP3 inflammasome pathway." (PMID 38020086, 2023). "Although NLRP3 expression in E-cadherin-positive tubular epithelial cells from focal segmental glomerulosclerosis (FSGS) and LN was somewhat higher compared to DN, IgAN, we could find NLRP3 mainly expressed in E-cadherin-negative tubular epithelial cells." (PMID 34716316, 2021).
hyperandrogenism (5 papers, 2019 to 2025). Excessive secretion of androgens from the adrenal glands or gonads. "Again, here, NF-κB whose expression is increased due to testosterone, and hyperandrogenism-induced endoplasmic reticulum (ER) stress can induce the formation of NLRP3 inflammasomes, ultimately leading to pyroptotic cell death in GCs." (PMID 39026050, 2024). "Our results showed that the mRNA expression level of NLRP3 in GCs was significantly higher in PCOS with hyperandrogenism group." (PMID 31448581, 2019). "They concluded that hyperandrogenism could trigger NLRP3 inflammasome activation resulting in low-grade inflammation in PCOS mice." (PMID 37446154, 2023). "Furthermore, authors suggested that TLR4 pathway may mediate hyperandrogenism-induced chronic low-grade inflammation in PCOS mice, possibly by leading to the activation of NLRP3 inflammasome via the downstream signaling molecule MyD88 and activation of NF-κB." (PMID 39026050, 2024).
immune deficiency (5 papers, 2021 to 2025). "Overall, the results demonstrated that NLRP3 is a crucial target by which the combination overcomes immunodeficiency in LPS/ATP-stimulated RAW264.7 macrophages." (PMID 33972672, 2021). "Given this significance, NLRP3 was investigated to determine if the ginsenosides jointly target this molecule to overcome immunodeficiency." (PMID 33972672, 2021). "Furthermore, both IFI16 and NLRP3 correlated negatively with CD4 T cell counts, indicating decreased levels in relation to HIV-related immunodeficiency." (PMID 39000248, 2024). "Altogether, whereas the associations with viral load were more complex and not significant for NLRP3, our data support that HIV infection induces IFI16 in human monocytes, and both IFI16 and NLRP3 expression is higher in PWH with more pronounced immunodeficiency (i.e., with lower CD4 T cell counts)." (PMID 39000248, 2024).
inflammatory bone diseases (5 papers, 2022 to 2025). "The NLRP3 inflammasome has been reported to be associated with the pathogenesis of inflammatory bone diseases." (PMID 38270300, 2024). "The NLRP3 inflammasome is closely associated with various arthritic conditions, and its abnormal activation is of great significance for the inflammatory responses as well as the development of immune diseases, and is a therapeutic target for the alleviation of inflammatory bone diseases." (PMID 37954594, 2023). "Therefore, the regulation of the autophagy/NLRP3 pathway is a potential method for the treatment of inflammatory bone diseases." (PMID 39679857, 2024). "Moreover, the interaction among the transcription factor forkhead box O1 (FoxO1), Propionibacterium acnes, NLR family pyrin domain-containing protein 3 (NLRP3) inflammasomes, and IL-1β may contribute to the pathogenesis of osteitis." (PMID 41303152, 2025).
left ventricular hypertrophy (5 papers, 2019 to 2025). Enlargement of the LEFT VENTRICLE of the heart. "In fact, the increase in plasma uremic toxins was associated with left ventricular hypertrophy and cardiac NLRP3 and NF-κB pathway activation in CKD patients." (PMID 41154550, 2025).
limb ischemia (5 papers, 2020 to 2025). A ischemia that involves the limb. "Tetrahydrocurcumin (THP) induces the polarization of M1 macrophages to M2 by inhibiting the TLR4/NF-κB/NLRP3 signaling pathway, thereby alleviating acute lung injury caused by limb ischemia-reperfusion in rats." (PMID 40538538, 2025).